TLR3 (toll like receptor 3)
Diseases named in the same sentence as TLR3 in open-access papers (continued):
Sharing a sentence is not in itself a finding about the gene and the disease.
tumor (continued). "Furthermore, these non-coding RNAs were also shown to promote tumor growth by stimulating secretion of autocrine insulin-like growth factor (IGF-1) and activating the NF-κB pathway via retinoic acid-inducible gene-1 (RIG-1) and toll-like receptor 3 (TLR3) signaling." (PMID 32528868, 2020). "Notably, RNAs isolated from parental tumor cells could not induce IL-1β expression, suggesting that unique RNA(s) in L-MPs is responsible for the TLR3 activation." (PMID 31649305, 2020). "Interestingly, in draining lymph nodes only the CD103+ cDC1 express TLR3 while CD11b+ cDC2 present there did not, suggesting that TLR3 expression is induced in CD11b+ cDC2 inside the tumor by an unknown mechanism." (PMID 30949170, 2019). "Moreover, in smokers a trend towards a worse prognosis and TLR3 protein expression in the tumor infiltrate was observed (p = 0.0856; HR = 1.497; CI = 0.945–2.372) and also considering cases expressing TLR3 on immune cells and not on tumor cells (p = 0.0463 Wilcoxon test)." (PMID 31582772, 2019). "Our results show that tumour growth was severely impaired by both intraperitoneal and intratumoural poly I:C administration, demonstrating for the first time the direct non-immune-mediated anticancer effect of the TLR3 agonist as a single therapeutic agent in human PCa cells in vivo." (PMID 25444175, 2015). "While the location of this SNP in the 3′ flanking region may alter mRNA expression/processing or gene product function (e.g., anti-tumor response, cell death), to our knowledge there are no published reports on the relationship between this TLR3 SNP and human disease." (PMID 24194738, 2013). "We found that the growth of cancer cells with TLR3 knockout was significantly decreased, which was rescued by wild-type TLR3 or NLS-TLR3 rescue, but not NES-TLR3 rescue, demonstrating the contribution of nucleus-localized TLR3 in promoting tumor progression." (PMID 40675966, 2025). "Interestingly, the activation of the CXCL10/CXCL11–CXCR3 axis and TLR3/TLR4 signaling pathways suggested that the combination of hyperthermia and radiotherapy could effectively reshape the tumor immune microenvironment and enhance tumor cell sensitivity to cytotoxic attacks." (PMID 41280655, 2025). "SQ20B-shcontrol cells, which are stably transfected with control plasmid, generate normal tumor spheres of circular shape, and SQ20B-shTLR3 cells, in which TLR3 is conditionally knocked down, do not produce tumor spheres, but cells stay rather scattered." (PMID 40647457, 2025). "We found that TLR3 knockout led to a remarkable decrease in liver metastasis in tumor-bearing mice, which was rescued by wild-type TLR3 or NLS-TLR3 rescue, but not NES-TLR3 rescue." (PMID 40675966, 2025). "In line with this, our in‐depth analysis revealed that RA‐induced NF‐κB and type I IFN activation in tumor cells depended on the cGAS/STING as silence of cGAS or STING, but not RIG‐1, MDA‐5, or TLR3, abolished NF‐κB and type I IFN activation." (PMID 36876644, 2023). "Growth of primary tumors receiving in situ Flt3L and TLR3/CD40 agonists was not altered by irradiating distant tumors, emphasizing the requirement for targeting the same tumor to achieve maximal tumor control by ISIM." (PMID 33110069, 2020). "On the other hand there is a report that TLR3 can directly induce apoptosis in human tumor cells It is suggested, that TLR signaling is involved in tumor proliferation but not in cancer initiation." (PMID 30976817, 2019). "Considering expression of TLR3 on both tumor and immune cells, NSCLC cases that expressed TLR3-s but not TLR3-t had a significantly worse prognosis compared with all other patients (p = 0.0093; Wilcoxon test)." (PMID 31582772, 2019).
tumor (continued). "A study in a murine model using an E7 peptide-based vaccine in combination with PADRE and a Toll-like receptor 3 (TLR3) agonist indicated better CTL responses and anti-tumor protection than the vaccine without the T helper epitope." (PMID 26556756, 2015). "In T cells, the ability of TLR3 signaling to obviate CD4- or APC-mediated costimulation and formation of memory T cells is a helpful feature for the design of cancer vaccines because costimulatory signals are absent in a tumor microenvironment." (PMID 32012718, 2020). "At the same time, the lactate in TME can inhibit TLR3 and its downstream IFN-I and the stimulator of interferon genes (STING), which accelerates the degradation of antigen, affects the cross-presentation ability of DCs, and thus fails to initiate the anti-tumor response." (PMID 33732237, 2021). "Given the dual-targeting of JOC-x to DSG2 and poly(I:C) to TLR3, we predict our JOC-poly(I:C) may exhibit dose sparing qualities by resulting in less non-specific binding of poly(I:C) to non-tumor TLR3 cells as well as targeting the host-directed therapeutic to tumors." (PMID 30992466, 2019). "Interestingly, even without addition of TAA, ARNAX decreased tumor growth, which can be explained either by DCs internalizing tumor debris containing TAAs and cross-priming CD8+ T-cells or TLR3 signaling facilitating chemotaxis of the pre-existing CTLs through cytokine production." (PMID 31695691, 2019).
cancer (261 papers, 2007 to 2026). A tumor composed of atypical neoplastic, often pleomorphic cells that invade other tissues. "To uncover the mechanisms underlying the pro-tumoral function of nuclear TLR3, we performed LC-MS mass spectrometry to identify TLR3-binding proteins in the nucleus of cancer cells." (PMID 40675966, 2025). "The mutation C37R, although not previously reported in a cancer context to our knowledge, was shown in our study to significantly impact protein structure and stability, and is proposed here for the first time as a novel cancer-related TLR3 mutation." (PMID 40847033, 2025). "Through performing the box plot analysis using the GEPIA2 database, we can understand the differential gene expression associated with different cancer types of the TLR3 gene." (PMID 40847033, 2025). "Hiltonol® acts as a critical immune adjuvant for cancer vaccines, whose mechanisms include TLR3 and melanoma differentiation-associated gene/protein 5 (MDA5)-mediated systems." (PMID 41149451, 2025). "The addition of the TLR3 danger signal in association with this immunization is expected to magnify the immune response induced in patients with cancer." (PMID 41149451, 2025). "Previous studies have already implicated N284I in impaired TLR3 signaling and increased susceptibility to viral infections53suggesting its pathogenic role beyond cancer." (PMID 40847033, 2025). "Poly (I:C), a TLR3 activator, directly causes apoptosis in cancer cells via a caspase-dependent pathway." (PMID 37005579, 2023). "Human NK cell lines for instance YTC12, YTS, and NK92 expressed high amounts of activated TLR3, causing cytotoxic killing effects on K562 cancer cells." (PMID 37936697, 2023). "According to our results, the mutation rates of TLR3 were 29% in all types of cancer and approximately 1% in patients with breast caricinoma." (PMID 36583248, 2023). "Mutations in the TLR3 genotypes are also found to be linked to the occurrence and development of carcinoma and are associated with the poor survival of the affected patients." (PMID 37822929, 2023). "Our study enriched the associations between TLR3 and cancers and proved that TLR3 had the potential to be a diagnostic and prognostic biomarker for KIRC, LGG and PAAD, especially an early diagnosis biomarker of KIRC." (PMID 36419829, 2022). "The upregulated expression of TLR3 was associated with sensitivity of cancer cells to erdafitinib (JNJ-42756493) and duvelisib (IPI-45), but it was associated with increased drug resistance to tyrothricin." (PMID 35165523, 2022). "Particularly, PC cells show high expression levels of TLR3 associated with increased cancer cell proliferation and with constitutive activation of the Wnt5a signaling." (PMID 34884547, 2021). "In parallel, in other cancer types, such as prostate, oral, esophageal, or gastric cancer, TLR3 expression appears to be associated with poor prognosis." (PMID 33147700, 2020). "In contrast to smac mimetic treatment, c-FLIP knockdown by siRNA transfection not only increased the level of Poly(I:C) cytotoxicity in the sensitive cell lines but also rendered all resistant cancer cell lines susceptible to TLR3-mediated death." (PMID 30158588, 2018). "Our findings clearly show that the dampening of TLR3 expression makes KRAS mutated cancer cells a better therapeutic target for oncolytic reovirus." (PMID 28422714, 2017). "Down regulation of TLR3 in the CRC cell line HCT116 which constitutively harbors KRAS mutation improves the anti-cancer activity of the reovirus." (PMID 28422714, 2017). "Since then, several studies have focused on examining the association of TLR3 SNPs with cancer risk." (PMID 26063214, 2015).
cancer (continued). "We systematically reviewed studies that focused on a collection of 12 SNPs located in the TLR3 gene and the details by which these SNPs influenced cancer risk." (PMID 26063214, 2015). "In this meta-analysis, we found that TLR3 rs5743312 was associated with an increased overall risk of developing cancer." (PMID 26063214, 2015). "The variant TLR3 genotype rs5743312 (C9948T, intron 3, C > T) was significantly associated with an increased cancer risk as compared with the wild-type allele (odds ratio [OR] = 1.11, 95 % confidence interval [CI] = 1.00–1.24, P = 0.047)." (PMID 26063214, 2015). "Here, we systematically reviewed published data and comprehensively analyzed and integrated all published studies on the relationship between TLR3 SNPs and cancer risk." (PMID 26063214, 2015). "TLR3 rs3775291 was also associated with an increased cancer risk in the Asian, hospital-based source of controls, and small sample size subgroups." (PMID 26063214, 2015). "In the stratified analysis, the variant genotype of the TLR3 rs3775290 polymorphism was associated with an increased cancer risk in the Asian subgroup." (PMID 26063214, 2015). "While TLR3 agonists have been shown to cause cell death in pancreatic β cells, endothelial cells, and cancer cells, a novel role of anthracycline induced TLR3 activation has been recently described in ICD." (PMID 26486085, 2015). "In summary, this meta-analysis indicated that the variant allele of TLR3 rs5743312 is potentially associated with increased cancer risks both in the whole collection of studies and in the large sample size subgroup." (PMID 26063214, 2015). "In our stratification analyses, TLR3 rs3775290 was found to be associated with cancer risk in Asian populations." (PMID 26063214, 2015). "However, the pro-tumoral roles of cancer cell aberrant TLRs, particularly TLR3 expression in cancer patients and the underlying mechanisms by which TLRs act as oncogenic proteins in the TME urgently require further elucidation." (PMID 40675966, 2025). "The generation and dissemination of CSCs has been proposed as the basis of metastases, which may explain worsened clinical outcomes associated with TLR3 expression in some cancer subtypes." (PMID 39988665, 2025). "In cancer, TLR3 expression has been linked to both favorable and poor prognoses, though the underlying mechanisms remain unclear." (PMID 39988665, 2025). "TLR-3 activation in cancer cells may enhance the production of pro-apoptotic proteins and increase the susceptibility of cancer cells to chemotherapeutic agents." (PMID 39124797, 2024). "Of note, the death signal transduction associated with TLR3 activation has a plastic component, since it results in the activation of apoptosis, necroptosis, or a form of lysosomal death, depending on the functional effectors present in cancer cells." (PMID 37414800, 2023). "Mechanistically, given that the activation of TLR3 relies on the signature molecules expressed on pathogens and cancer cells, namely PAMP (pathogen-associated molecular patterns), PAMP may be closely associated with the tumorigenicity of TLR3." (PMID 35000541, 2022). "But TLR3 was associated with the clinical outcomes of various cancers." (PMID 34266404, 2021). "Interestingly, the results also suggested that the upregulation of TLR3 in KIRC was linked to a better prognosis of patients in cancer Stages 2 to 4 and tutor Grades 3 to 4 (All p < 0.05)." (PMID 34531911, 2021). "However, TLR3 appears to have a dual role in tumors, since studies have associated TLR3 levels with either good or poor clinical outcome in different cancer types." (PMID 33147700, 2020). "Interestingly, this study also found that combining the TLR7 knockout with TLR3 and TLR9 knockouts lead to the spontaneous emergence of cancer in the triple-TLR-deficient mice, suggesting a role for TLR3 and 9 in cancer immuno-surveillance." (PMID 33202596, 2020). "Summary of TLR3 expression and association with clinical outcome in human cancer types." (PMID 33147700, 2020).
cancer (continued). "Furthermore, we also observed for the first time that TLR3 expression on cancer cells is significantly associated with cleaved caspase-3 expression in a cohort of 45 human primary adenocarcinoma NSCLC." (PMID 32093313, 2020). "To date, the correlation between TLR3 protein level and the susceptibility of the cancer cells to polyI:C is unknown." (PMID 28427199, 2017). "Constitutive expression of endogenous TLR3 in cancer cells could be an indicator of susceptibility or resistance to polyI:C stimulation." (PMID 28427199, 2017). "TLR3 single nucleotide polymorphisms (SNPs) could possibly affect cancer susceptibility and could therefore serve as potential biomarkers to evaluate cancer risk." (PMID 26063214, 2015). "We included a meta-analysis for hotspot SNPs (rs3775290, rs3775291, rs3775292, and rs5743312) that have been described in at least three published studies to enhance the comprehensiveness of our assessment into the association between TLR3 SNPs and cancer risk." (PMID 26063214, 2015). "Clarifying this association could advance our knowledge of the influence of TLR3 single nucleotide polymorphisms (SNPs) on cancer risk." (PMID 26063214, 2015). "Reliable results could be obtained in these cases based on the high quality of the studies designed to explore the real associations of TLR3 SNPs with cancer risk." (PMID 26063214, 2015). "Second, the pooled sample size was relatively limited and therefore could support only preliminary evaluations of the association between various TLR3 polymorphisms and the incidence of various types of cancer." (PMID 26063214, 2015). "After data integration, our findings suggest that the TLR3 rs5743312 polymorphism may contribute to an increased cancer risk." (PMID 26063214, 2015). "The TLR3 SNPs that exhibit the most variability are rs3775290 and rs3775291; however, their relationship with cancer risk remains unclear." (PMID 26063214, 2015). "However, after data integration, we concluded that this SNP is the only significant site in the TLR3 gene with respect to cancer risk." (PMID 26063214, 2015). "The finding that TLR3 down-regulation occurred in a subset of cancers and was associated with recurrence may mean that some cancers are more successful than others in escaping detection by the immune system." (PMID 17280610, 2007). "Thus, a comprehensive analysis integrating all studies on TLR3 SNPs and cancer risk is needed." (PMID 26063214, 2015). "We propose an integrative framework in which TLR3 signaling influences cancer cell fate according to cellular and microenvironmental context." (PMID 42278599, 2026). "Human cancer tissue analyses further confirm the correlation of high nuclear TLR3 with poor response to neoadjuvant chemotherapy and worse prognosis of patients." (PMID 40675966, 2025). "Accordingly, patients with higher cancer cell nuclear TLR3 expression had shorter overall survival (OS) and disease-free survival (DFS) after surgery." (PMID 40675966, 2025). "The JAK1/TLR3/PRMT5/c-Myc axis provides potential targets for cancer and reasonable evidence for predicting chemotherapeutic efficacy and patients' prognosis." (PMID 40675966, 2025). "Recent studies demonstrated that human TLR3 can be ectopically expressed in cancer cell endosomes and that its expression levels in human ESCC cells are associated with prognosis." (PMID 40029556, 2025). "Perhaps structured RNA with duplexed parts in its sequence able to mediate TLR3 activation is liberated from cancer cells." (PMID 40029556, 2025). "Nucleotide- or deoxynucleotide-based adjuvants (unmethylated CpG deoxynucleotides [CpG ODN]24–26, a TLR9 agonist, and polyincosinic-polycytidylic acid [Poly I:C]27, 28, a TLR3 agonist ) are currently used for cancer immunotherapy." (PMID 40832663, 2025).